CD4 (CD4 molecule)
Diseases named in the same sentence as CD4 in open-access papers (continued):
Sharing a sentence is not in itself a finding about the gene and the disease.
tumor (continued). "Further, HLA class II-dependent help from CD4-positive TILs might significantly support anti-tumor immune response (the term TILs will be used throughout the manuscript describing the population of tumor infiltrating T-lymphocytes mainly consisting of CD3-, CD4- and CD8-positive cells)." (PMID 29490700, 2018). "We demonstrated that the diminished occurrence of CD4+ TH cells and CD8+ TC cells in the a2V-KO tumor as well as in the periphery (bottom rows) creates a pro-tumorigenic environment that is conducive for tumor growth and metastasis." (PMID 30237863, 2018). "MiR-7-5p expression in the miRmine data sets was very high in pancreas beta cells and high in various plasma samples, testis, sperm, placenta, serum, salivary exosomes, CD4+ T cells and CD19+ B cells from blood, and different tumor tissues." (PMID 30081835, 2018). "In relation to the increase in T cells, our results confirmed the induction of genes as Cd3g, Cd4, Il6, Il10 and Il12a in spleens of Ats1-KO mice, independently of the absence or presence of B16F1 tumours." (PMID 30166561, 2018). "In patients <75 years, the density of CD4+, CD8+, and PD-L1 in TAICs showed a positive significant correlation with PD-L1 expression in tumor cells (TCs), while a lower correlation was observed in the elderly population." (PMID 30216999, 2018). "Further analysis of tumor tissues and microenvironment lymphocytes showed that 1-MT significantly enhanced Th1cells CD3+CD4+CD25− alone and with TL/DC-TL (23.3%, 19.2%, and 21.6%) respectively in comparison to PBS (13.4%)." (PMID 29959375, 2018). "Previous studies established that presence of CD4+ Th1 cells and cytotoxic CD8+ T cells (CTLs) in tumor microenvironment presents positive prognostic sign, while presence of Treg and Th2/Th17 cells indicates lower survival of patients with CRC." (PMID 29849497, 2018). "While CD103+CD8+ TILs isolated from NSCLC demonstrated greater cytotoxic capacity toward tumor cells than their CD103− counterparts, the functional characteristics of CD103+CD4+ TILs remain largely unexplored." (PMID 30505306, 2018). "In cancers, these cells suppress CD4 and CD8 T cell-mediated anti-tumor responses by the nitration of the T cell receptors." (PMID 29765907, 2018). "Two days post last treatment of ALX148, a significant increase in tumor infiltrating CD8+ (p<0.0001) and CD4+ T cells (p<0.0001) was seen in mice receiving combination treatment compared to vehicle control." (PMID 30133535, 2018). "Antitumoral activity was shown for CXCR4 antagonist BL-8040 in tumor bearing mice, where it induced robust mobilization of CD4+ and CD8+ T lymphocytes and DC in numbers that were significantly higher compared to tumor free naïve counterparts." (PMID 30622535, 2018). "We found significant positive correlation between immunoexpression of PD-L1 in tumor cells and the number of infiltrating Foxp3+ cells in both tested groups of OSCC and between PD-L1 and number of CD4+ cells in OSCCPP group." (PMID 28669079, 2018). "Similar downtrend of CD4+/CD8+ T-cell infiltration and IFN-γ expression in tumor tissues of ABX cotreated mice was detected by immunohistochemical analysis." (PMID 30305604, 2018). "This suggests that the improvement in survival was dependent upon the CD4+ T cells expressing the B7H6-specific CAR/T-bet (∆TBOX), which functions as a mediator of the immune response against the tumor." (PMID 29515240, 2018). "Four weeks later, 50ul of peripheral blood from each animal were collected to check for CD4+/CD8+ reconstitution, using flow cytometric analysis, before tumour establishment." (PMID 29440650, 2018). "Our first relevant result is the induction of a massive infiltration of T lymphocytes into the bladder, both CD4+ and CD8+ T cells in M. brumae-treated tumor-bearing mice compared to the basal infiltration that is observed in non-treated tumor-bearing mice." (PMID 30305693, 2018).
tumor (continued). "The results shown that combined SEP and αPD-L1 presented significant synergistic antitumor effects, increased the frequency of CD8+ and CD4+ T cells in spleen and tumor, cytotoxic activity of CTL in spleen, and IL-2 and IFN-γ levels in splenocytes and tumor." (PMID 29317734, 2018). "This intervention was shown to induce CD4+ and CD8+ anti-tumour T-cell responses against several epitopes." (PMID 29875199, 2018). "We characterized the expression of PD-L1 in tumor and TAICs, and evaluated the density of TAICs expressing CD4, CD8, and CD33 on sequential whole tumor sections from resected stage II-IV LADCs." (PMID 30216999, 2018). "We report the case of a 72-year-old woman presenting with a pleomorphic tumor of the left breast with a dense infiltration by OGCs and T lymphocytes with a 10:1 predominance of CD8+ over CD4+ cells." (PMID 30153845, 2018). "Loss of CD11b expression or function promotes immune suppressive gene expression in macrophages in vitro and TAMs in vivo, increases FoxP3+ CD4+ T cells and decreases CD8+ T cell recruitment to tumors and increases tumor growth." (PMID 30568188, 2018). "Using immunohistochemical analysis, we counted the numbers of CD4+, CD8+, and Foxp3+ T lymphocytes both in the invasive front and tumor bulk." (PMID 29732001, 2018). "We also found that the CD4+/CD8+ T-cell infiltration and IFN-γ expression in tumor tissues were distinctly upregulated through this combination treatment." (PMID 30305604, 2018). "Expression and absolute numbers of CD56, CD57, CD4 and CD68 were similar in resected tumor in both groups." (PMID 30229370, 2018). "Others claimed that extracellular galectin-3 induces apoptosis of CD4 or CD8 T cells in the tumors and can suppress IFN-γ secretion of human cytotoxic T cells in tumor." (PMID 29849497, 2018). "Specifically, MIF expression in the tumor cells reduces the abundance of activated DCs in the tumor microenvironment, and also suppresses the increase in IFN-gamma producing CD4+ and CD8+ T cells within the tumor." (PMID 29864117, 2018). "Cured mice remained tumor-free for the remainder of their natural lives and were protected from tumor re-challenge by CD8+ and CD4+ T cells and natural killer cells." (PMID 30560130, 2018). "Our previous studies demonstrated that DC-based vaccines were safe and induced the expansion of circulating CD4+ T cells and CD8+ T cells that are specific for tumor antigens, which was synergistically enhanced by the combination of lenalidomide." (PMID 29967612, 2018). "Assessment of tumor immune cell populations showed that treatment slightly enriched CD8+ T cells and CD4+ T cells; however, infiltration of immune cells was negligible, and thus, immune cells were not responsible for the increase in [18F]FDG uptake." (PMID 30117062, 2018). "While IFN-α abrogates the suppressive activity of CD4+ CD25+ Foxp3+ Tregs, thus hampering tumor evasion, IFN-I signal blockade boosts the ICB-induced antitumor response by favoring the effector T cells to Tregs ratio." (PMID 29619026, 2018). "According to our data, a prolonged incubation of lymphocytes with IL-2 leads to an activation of a subpopulation of CD4+CD25+ cells, which is able to kill HLA-negative tumor cells through the FasL-Fas interaction." (PMID 29850628, 2018). "CD4+ T helper cells and CD8+ T cells that synthesize INF-γ cytokines are believed to exert an antitumor effect by killing tumor cells and restricting tumor growth." (PMID 29662489, 2018). "Activated CD4 T-cells release pro-inflammatory cytokines, such as IFNγ, which in turn, upregulate MHC-II expression on tumours to allow for direct recognition by CD4 T-cells." (PMID 29570634, 2018). "In line with the immunomodulatory role of the tumor microenvironment, CD8+ and CD4+ TILs expressed high levels of inhibitory receptors 2B4, CTLA-4, and PD-1, with the highest levels found on CD103+ TILs." (PMID 30505306, 2018).
tumor (continued). "Tumor inhibition in mice immunized with mD8-FAT1-OMVs was accompanied by the accumulation of infiltrating CD8+ and CD4+ T cells and by the concomitant reduction of regulatory T cells (CD4+/Foxp3+) and myeloid-derived suppressor cells (MDSCs)." (PMID 30416985, 2018). "In this regard, the same rule is applicable to the CD4 and CD8 T cell interplay, as being part of the cancer immune cycle: any disruption of crucial cross-talk events results in a failure of tumor growth control." (PMID 29032503, 2018). "When used in combination, however, pP1A and ICBs significantly increased IFNg and IL12 production but also CD4 and CD8 T cell infiltration 10 days after tumor implantation." (PMID 30356111, 2018). "In a therapeutic vaccination setting, TAT-E7-GM-CSF provided a strong anti-tumor effect dependent on CD8 T cells and to a lesser extent on CD4 T cells." (PMID 29508006, 2018). "In order to conduct a non-biased, unsupervised analysis of phenotypic differences between CD4+ T cell compartments, cohorts of mice were injected with LLC1 tumor cells and tumors were allowed to grow for 3 weeks." (PMID 29338031, 2018). "We isolated T lymphocytes and preformed CD4+IFN-γ+ and CD8+ IFN-γ+ double staining for exploring more possible mechanism of anti-tumor activity in mice immunized with hDKK1-hHSP70 fusion vaccine." (PMID 29416605, 2018). "Previous studies mainly focused on the expression of PD-L1 on tumor cells and its role in CTL inhibition, and PD-L1 expression on APCs and its potential role in the dysfunction of CD4+ T cells remain neglected." (PMID 30333036, 2018). "Some tumor cells express MHC class II, and in such cases, cytotoxic CD4+ T cells have been shown to mediate direct cytotoxic effects via the Fas/Fas ligand or perforin/granzyme pathway." (PMID 30083157, 2018). "Immunological data showed a significantly higher presence of CD4+ and CD8+ T cells in circulation and infiltration to tumor sites in the Per1/2−/− mice." (PMID 29581861, 2018). "In agreement with the relative dominance of CD8+ T cells in the tumor tissue, Sipa1−/− CD8+ T cells showed greater chemotactic activity than Sipa1−/− CD4+ T cells." (PMID 29500416, 2018). "This could be the result of a partially retained ability of host immune system to control the expansion of the tumour cell pool, consistently with the observation that cHL generally occurs in HIV-positive patients with a moderate level of immune deficiency, as indicated by CD4+ T-cell count." (PMID 29799516, 2018). "Mice immunised with these constructs generated antigen-specific CD4, CD8 or mixed responses and were protected from a subsequent tumor challenge." (PMID 30200528, 2018). "Within the tumor environment, purified TIL-B were reported to suppress the proliferation of CD4+, CD8+, and CD4+CD25− T cells, as well as NK proliferation in response to IL-15." (PMID 29568299, 2018). "In 4T1 tumor models, mice treated with Tα1-Fc, compared with Tα1, showed an increased expression of CD86 and promoted CD4+ T lymphocytes and CD8+ T lymphocytes infiltrating tumor tissues." (PMID 30120362, 2018). "CP1 increased T cells not only in the tumor stroma and periphery, but also intra-tumorally, consisting of both CD8 and CD4 TILs." (PMID 29686284, 2018). "We previously reported that the increases of both CD4+ and CD8+ memory T cells in the tumor-free animals correlated with animal protection after treatment with NPS." (PMID 29954062, 2018). "By Inter-Organ Clone Tracking analysis, we demonstrated that anti-CD4 mAb treatment increased the diversity and combined frequency of CD8+ T cell clones that overlapped among the tumor, draining lymph node (dLN), and peripheral blood repertoires." (PMID 30733724, 2018). "Both CD4+ and CD8+ T cells epitopes from Survivin protein are important for induction of effective anti-tumor immune response." (PMID 30631324, 2018).
tumor (continued). "In the tumor, we observed an increase in CD45+ tumor-infiltrating cells in the PBS/P2Et group in both models, which appeared to be CD3+, CD4+, or CD8+ T cells and were also more activated, compared with the control group." (PMID 30234017, 2018). "In the DALM and the T1a adenocarcinoma removed a few years before the kidney transplant, CD4+ and CD8+ T lymphocytes had evenly infiltrated the neoplasms." (PMID 29915171, 2018). "Further studies demonstrated that endogenous Gal-1 in CD4+, but mainly in CD8+T cells, acts as a negative regulator of anti-tumor immunity." (PMID 30319642, 2018). "During the induction phase of bacterial infection, CD8+ T cells are the only effectors responsible for tumor clearance; whereas, in the memory phase the clearance also involves CD8+ and CD4+T cells." (PMID 29568324, 2018). "The increase of both CD4+ and CD8+ T cells along with the reduction of Tregs in tumor-bearing host confirmed the immune stimulation exerted by B-9-3." (PMID 30079021, 2018). "In tumor pathogenesis, the activation of these molecules triggers signalling pathways which primarily prevent the function of CD8+ and CD4+ cells." (PMID 29854832, 2018). "Surprisingly, helper/regulatory CD4+ T cells (CD4+, CD45+), known to promote tumor growth, were unchanged, and additional flow cytometry analysis by CD25 and FOXP3 staining showed no change in regulatory T cells." (PMID 30458886, 2018). "In one study, in which 45 tumor samples from GBC patients and 65 benign gallbladder tissues were examined, increased frequencies of CD4+, CD8+ T cells and DCs were observed in GBC samples, which significantly correlated with prolonged patient survival." (PMID 29600445, 2018). "In the present study, we focused on the function of PLD2 in CD4+ and CD8+ T cells to elucidate the pathological function of PLD2 in tumor growth." (PMID 29674728, 2018). "Other immune cells, such as CD4+ helper T cells or FOXP3+ regulatory T cells, or even tumor cells themselves stimulate or suppress the immune response." (PMID 30619761, 2018). "Taken together, the frequency of heavily exhausted T cells (PD-1+LAG-3+) in the population of peripheral CD4+ and CD8+ T cells increases in BLV-infected cattle bearing tumor." (PMID 29914540, 2018). "We determined the frequencies of CD4+ and CD8+ T cells among the total CD3+ T cell pool in paired tumor, lung, and blood samples of 33 NSCLC patients." (PMID 30505306, 2018). "The data demonstrates increased numbers of CD4+ and CD8+ TILs, macrophages and neutrophils, within primary tumours or metastatic IL-33-expressing tumours when compared to metastatic tumours alone." (PMID 29440650, 2018). "The expression of CCR5 on CD4+ and CD8+ T lymphocytes has been described to be essential for an efficient tumor rejection in mouse model of Lewis lung adenocarcinoma and pancreatic adenocarcinoma." (PMID 30319638, 2018). "In terms of an immune response, synergy was observed in the pixatimod and anti-PD-1 treatment group as significant increases in both tumor-specific CD8 and CD4 effector memory and central memory T cells were evident." (PMID 29898788, 2018). "The tumor margin was enriched for CD8+ T cells; whereas the tumor stroma comprised increased CD4+ T cells, B cells and CD11c+ cells." (PMID 30042403, 2018). "miR-155 expression in T cells is required for maintaining the number of IFNγ-expressing CD4+ and CD8+ T cells and suppressing tumor growth." (PMID 30046565, 2018). "c and fraction of tumor border CD8 T cells positive for granzyme B (Gzm B) and tumor border CD4 T cells positive for Foxp3." (PMID 30285905, 2018). "In contrast, by measuring PD-1, PD-L1, CD4 and CD8 by IHC on sequential tumor slices, it has been possible to identify some immune checkpoint inhibitor-responsive melanom patients." (PMID 29993362, 2018). "CD4 is a co-receptor for Ag recognition and presentation, whereas CD8+ T cells can lysis tumor cells." (PMID 30120362, 2018).
tumor (continued). "Altogether, our results support previous findings indicating that the tumour microenvironment induces the expression of PD-L1 in CD14+-TAMs, and that their interaction with CD4+PD-1+ cells triggers T-cell exhaustion, thus allowing tumour propagation." (PMID 30285662, 2018). "In vivo, using liver-specific inducible MYC transgenic mice fed MCD diet, blocking CPT with the pharmacological inhibitor perhexiline decreased apoptosis of intrahepatic CD4+ T cells and inhibited HCC tumor formation." (PMID 29795111, 2018). "CD4+ and CD8+ T-cell responses can mediate global anti-tumor effects at distant loci and direct tumor cell killing." (PMID 30514385, 2018). "Percentage of total CD4+ T cells and CD62L−CD44+ effector CD4+ T cells as well as their effector functions in spleen, TDLN and tumor were similar between Eomesfl/fl and Eomesfl/flCd4Cre mice." (PMID 30619337, 2018). "No tested parameters including age of onset, lymphocyte counts, proviral load, tumor cell type, and B-cell occupancy in blood were significantly correlated with PD-1+LAG-3+CD4+ and PD-1+LAG-3+CD8+ T-cell populations of the EBL animals." (PMID 29914540, 2018). "Therefore, the observed positive effect of OX40/OX40L co-stimulation on tumor rejection, through CD4+/CD8+ T cell proliferation, prevention of T cell death, and prevention of tolerance induction, is caused by an unknown mechanism independent of IL-12p70 upregulation." (PMID 29867960, 2018). "Immunohistochemistry for CD45, CD4, CD8, programed death ligand 1 (PD-L1), and programed death 1 (PD-1) was performed on sections of surgical tumor specimens and peripheral blood mononuclear cells (PBMCs)." (PMID 29910795, 2018). "In both tumor models, IFN-γ secretion, as indicator for T cell activation, was highest when PTM+ CD4+ and PTM+ CD8+ T cells were combined." (PMID 30214445, 2018). "On the other hand, CD4 and CD8 T cell responses frequently fail to maintain proper function during tumor remissions." (PMID 29032503, 2018). "T cells in tumors—the so-called tumor infiltrating lymphocytes (TIL), which include both CD4+ and CD8+ T cells, have compelling clinical relevance as a critical denominator for OS in cancer patients." (PMID 30079021, 2018). "Genetic ablation of Chitinase 3-like 1 (Chi3L1) in fibroblasts in vivo attenuated tumor growth, macrophage recruitment, and reprogramming to an M2-like phenotype, enhanced tumor infiltration by CD8+ and CD4+ T cells, and promoted a Th1 phenotype." (PMID 30380628, 2018). "Our results clearly showed that nTreg and tumor-derived γδ Treg cells have a significantly higher glucose uptake than control naive CD4+ and CD8+ T cells, as well as CD4+CD25− effector T cells." (PMID 29339767, 2018). "This comprehensive profile indicates that T cells from MelTIL015 were present in large numbers and had penetrated the tumor, that CD4+ and CD8+ T cells were both activated (PD-1+OX-40+), and the high level of PDL1 in the tumor suggests secretion of IFN-γ." (PMID 30042403, 2018). "Immunohistochemistry confirmed increased tumor infiltration of cytotoxic CD8+ T cells and decreased regulatory CD4+ T cells in the combination group." (PMID 30854331, 2018). "More specific flow-cytometric analysis confirmed 4- to 5-fold increases in the percentage of tumor-infiltrating CD8+ and CD4+ T cells, with concomitant reduction in the percentage of CD4+/FoxP3+ regulatory T cells (Tregs)." (PMID 29433938, 2018). "Until now only few studies investigated the contribution of both CD4 and CD8 T cell responses in tumor models with autologous immunity." (PMID 29032503, 2018). "In our study, PD-L1 tumor cell expression was 13.8% of the ccRCC cases with SP263 clone and it was correlated with higher levels of PD-1, CD4, and CD8." (PMID 30144808, 2018). "After NPS, rapid increases of specific NK and NKT-cell subsets appear in liver, as well as by CD8+ and CD4+ effector memory and central memory T-cell responses in the HCC tumor microenvironment (TME), spleen and blood." (PMID 29533981, 2018).